NLRP1 (NLR family pyrin domain containing 1)
Diseases named in the same sentence as NLRP1 in open-access papers (continued):
Sharing a sentence is not in itself a finding about the gene and the disease.
preeclampsia (7 papers, 2019 to 2025). Preeclampsia is a hypertensive disorder of pregnancy that is characterized by new-onset hypertension with proteinuria presenting after 20 weeks of gestation, and depending on mild or severe forms may initially present with severe headache, visual disturbances, and hyperreflexia. "Preeclampsia is associated with abnormal activation of cells from the innate immune system, and the peripheral blood monocytes from preeclamptic pregnant women have higher endogenous activation of NLRP1/NLRP3 inflammasomes than that from normotensive pregnant women." (PMID 37228386, 2023). "Our study demonstrates that the expression level of NLRP1 is upregulated in human trophoblasts in placenta samples from preeclampsia patients compared to normal pregnant women." (PMID 40242759, 2025). "Numerous studies have demonstrated an upregulation of NLRP1 and Caspase-1 in the placenta of preeclampsia, suggesting that the NLRP1 inflammasome mediates inflammatory responses and contributes to placental injury in preeclampsia." (PMID 40242759, 2025). "There is a higher endogenous activation of NLRP1/NLRP3 inflammasomes in the monocytes from preeclamptic women than normotensive pregnant women, but Silibinin can inhibit NLRP1/NLRP3 inflammasomes in monocytes from pregnant women with preeclampsia." (PMID 36560538, 2022). "In addition, expression of NLRP1 is significantly higher in the placenta from preeclamptic pregnant females compared to normal pregnant females, but vitamin D treatment can decrease NLRP1 expression in the placental explants from women with preeclampsia." (PMID 36496806, 2022).
inflammatory skin disease (6 papers, 2022 to 2025). Inflammatory skin disorders covers a broad category that includes many conditions ranging in severity, from mild itching to grave medical health complications These disorders are common in people of all ages and races. "This is why NLRP1 and its genetic variants are key therapeutic targets in a wide variety of autoimmune and inflammatory disorders, mainly in inflammatory skin diseases." (PMID 39290706, 2024). "The auto-inhibitory PYD domain of NLRP1 is the first region that includes A54T, A66V and M77T mutations resulting in rare monogenic inflammatory skin diseases." (PMID 36426349, 2022). "Similarly, gain-of-function mutations in NLRP1 result in abnormal NLRP1 inflammasome activation and are associated with skin inflammatory diseases and juvenile-onset recurrent respiratory papillomatosis (JRRP)." (PMID 41087719, 2025). "NLRP1 is described as the main skin inflammasome, and its importance is also mentioned concerning inflammatory skin diseases such as psoriasis." (PMID 39290706, 2024). "Targeting the activation of NLRP1 in epidermal keratinocytes represented a potential therapeutic strategy for NLRP1-dependent inflammatory skin disease and cancer." (PMID 35633405, 2022). "Among these, extensive research has focused on the roles of inflammasomes formed by NLR family members (e.g., NLRP1 and NLRP3) and the AIM2-like receptor family member AIM2 in inflammatory skin diseases." (PMID 41383588, 2025).
injury (6 papers, 2011 to 2023). Damage inflicted on the body as the direct or indirect result of an external force, with or without disruption of structural continuity. "The discrepancies observed in our model versus the prior studies in rats underscore the need for further investigation to develop additional mechanistic insight into the role of the NLRP1 inflammasome following traumatic brain injury." (PMID 27199506, 2016). "Furthermore a downregulation of Nlrp1 inflammasome, which is necessary for IL-1β synthesis, has been described in trauma patients." (PMID 28255201, 2017). "Inflammasome activation was recently shown to be induced in acute brain injury as well, thus the NLRP1 inflammasome may constitute an important component of the CNSs' response to traumatic brain injury." (PMID 22523490, 2012).
toxoplasmosis (6 papers, 2014 to 2023). A parasitic disease contracted by the ingestion or fetal transmission of toxoplasma gondii. "Susceptibility to human toxoplasmosis was found to map to alleles of the NALP (NLRP1) gene and NALP1 was shown to contribute to the control of parasite growth in a human monocyte cell line." (PMID 33324583, 2020). "The NLRP1 rs12150220 polymorphism causes increased NLRP1 and IL-1β processing and have been associated with protection against infectious comorbidities, such as cytomegalovirus, toxoplasmosis, rubella, varicella, and parasitic diseases, in pediatric patients with ALL." (PMID 37577033, 2023). "This method of toxoplasmosis control is distinct from that observed in macrophage-resistant T. gondii, in which the activation of NLRP1 inflammation leads to rapid cell death." (PMID 36839525, 2023). "The Toxo1 locus on chromosome 10, which controls rat resistance to toxoplasmosis, maps within a region containing the inflammasome sensor Nlrp1 gene." (PMID 24626226, 2014). "Our results are consistent with those of previous studies, that is, T. gondii triggers NLRP3 or NLRP1, which leads to parasite restriction and resistance to toxoplasmosis, and p38 MAPK is important for the regulation of NLRP1 or NLRP3 inflammasome activation and IL-1β secretion." (PMID 33712075, 2021). "The contribution of interactions between human toxoplasmosis and the inflammatory process indicates that the expression of IL-1 in human monocytes depends on ASC and caspase-1, which is an adapter protein that binds caspase-1 to NLRP3/CARDB or NLRP1/caspase-5 in the flammomasome." (PMID 36839525, 2023).
autoimmune thyroid disease (5 papers, 2011 to 2021). Inflammatory disease of the thyroid gland due to autoimmune responses leading to lymphocytic infiltration of the gland. "Alkhateeb and colleagues have reported the correlation between single nucleotide polymorphisms of the NLRP1 gene and susceptibility to autoimmune thyroid disease; this may explain the changes in NLRP1 expression observed in the AIT patients in this study." (PMID 29915579, 2018). "A study explored the link between inflammasomes and autoimmune thyroiditis, and revealed the activation of NLRP1, NLRC4, and AIM2 inflammasomes in the thyroid tissues from patients with AIT." (PMID 34234669, 2021). "Correlation between NLRP3, NLRP1, NLRC4, absent in melanoma 2 (AIM2), ASC, caspase-1, IL-1β, and IL-18 expression in the autoimmune thyroiditis group." (PMID 29915579, 2018).
Cerebral ischemia (5 papers, 2022 to 2023). Restriction of arterial blood supply to the brain associated with insufficient oxygenation to support the metabolic requirements of the tissue. "This suggested that neuronal NLRP1 inflammasome activation contributes to the inflammatory response following cerebral ischemia." (PMID 37822799, 2023). "Double immunofluorescence staining for NeuN/Caspase1, NeuN/GSDMD, NeuN/IL-1β, MAP2/ASC, MAP2/GSDMD and NLRP1/GSDMD further confirmed that iTBS post-treatment is capable of inhibiting cerebral ischemia-induced pyroptosis of neuron in peri-infarcted area rather than at the border of infarcted core." (PMID 35690810, 2022). "To further investigate whether MFSCE attenuates neuroinflammation after cerebral ischemia, we determined the expression of NLRP inflammasome-associated proteins, including NLRP1, NLRP3, ASC, CL-caspase-1, CL-caspase-11, IL-1β, and IL-18 in the ischemic cortex using Western blotting." (PMID 35454994, 2022). "The increased expression of NLRP1 and NLRP3 is also related to cerebral ischemia injury." (PMID 36142849, 2022). "However, the mechanisms of the activation of NLRP1 and NLRP3 receptors during cerebral ischemia remain unknown." (PMID 36142849, 2022).
coronary artery stenosis (5 papers, 2020 to 2025). "NLRP1 levels were associated with the severity of coronary artery stenosis in CAD patients." (PMID 40124544, 2025). "The study has found that the level of NLRP1 is related to the severity of coronary artery stenosis in patients with PCHD." (PMID 40387676, 2025). "Whether the level of NLRP1 is related to the severity of coronary artery stenosis in patients with coronary artery disease (CAD) has not been reported." (PMID 37214347, 2023). "However, whether NLRP1 will play a similar role in the occurrence and development of coronary atherosclerosis and whether the level of NLRP1 is positively related to the degree of coronary stenosis in patients with coronary artery disease have not been reported yet." (PMID 37214347, 2023).
diabetic retinopathy (5 papers, 2021 to 2023). "In the skin NLRP1 induction may lead to skin hyperinflammation and carcinoma and in the eye, NLRP1 is associated with diabetic retinopathy and acute glaucoma." (PMID 34169069, 2021). "miRNA miR-590-3p, which has been proved to play an active role in inflammation, could directly target NLRP1 and NOX4 and inhibit pyroptosis in diabetic retinopathy through the NOX4/ROS/TXNIP/NLRP3 pathway." (PMID 35957838, 2022).
leprosy (5 papers, 2015 to 2025). Leprosy is a chronic infectious disease affecting primarily the skin and peripheral nervous system. "The NLRP1 combined haplotype rs2137722/G-rs12150220/A-rs2670660/G was associated with paucibacillary leprosy suggesting that NLRP1 might be involved in the susceptibility to leprosy." (PMID 29643852, 2018). "Analysis on NLRP1 and NLPR3 inflammasomes showed significant correlations between caspase-1 and IL-1β levels in Borderline leprosy, compared to the VV and TT forms of leprosy." (PMID 37887741, 2023). "SNPs in NLRP1 and NLRP3 genes were analyzed in Brazilian leprosy patients." (PMID 29643852, 2018).
multiple sclerosis (5 papers, 2013 to 2024). A progressive autoimmune disorder affecting the central nervous system resulting in demyelination. "Animal studies lend further support to the role of NLRP1 in susceptibility to multiple sclerosis." (PMID 28623311, 2017). "Since then, single nucleotide polymorphisms (SNPs) in NLRP1, NLRP3 and NLRC4 have been associated with many autoimmune diseases including IBD, celiac disease, multiple sclerosis and autoimmune diabetes." (PMID 34177937, 2021). "Both NLRP1 and NLRP3 exhibited increased expression in RE brain specimens relative to controls with mesial temporal sclerosis and multiple sclerosis." (PMID 24330827, 2013). "A small-molecule inhibitor (MCC950), specifically targeting NLRP3 inflammasome activation (ASC oligomerization) but not AIM2, NLRC4 or NLRP1 inflammasomes, was able to attenuate mouse models of multiple sclerosis and Parkinson’s disease." (PMID 34177937, 2021).
myocardial infarction (5 papers, 2022 to 2025). Gross necrosis of the myocardium, as a result of interruption of the blood supply to the area, as in coronary thrombosis. "Our results indicate that NLRP1 levels increase with the progression of coronary heart disease, from healthy individuals to those with unstable angina to those with acute myocardial infarction." (PMID 41189992, 2025). "We speculate that NLRP1 expression may be used as an index to predict myocardial infarctions." (PMID 37492291, 2023). "In addition, myocardial infarction in mice and heart failure in rats are related to the regulation of autophagy, and myocardial infarction is also related to the nucleotide binding oligomerization domain like receptor 1 (NLRP1) inflammatory pathway." (PMID 35566359, 2022). "This suggests that NLRP1 may contribute to disease progression by persistently amplifying inflammatory signaling, which aligns with the well-established principle that the magnitude of the inflammatory response influences the prognosis of acute myocardial infarction." (PMID 41189992, 2025). "The role of NLRP1 and NLRC4 inflammasomes after acute myocardial infarction (MI) is poorly understood." (PMID 40332346, 2025).
acute myeloid leukemia (4 papers, 2020 to 2023). Acute myeloid leukemia (AML) is a group of neoplasms arising from precursor cells committed to the myeloid cell-line differentiation. "Surprisingly, induction of pyroptosis in THP-1 cells and other AML (acute myeloid leukemia) cells by talabostat is mediated by CARD8 rather than by NLRP1, demonstrating that CARD8 is also able to form a type of inflammasome." (PMID 32640751, 2020). "As in acute myeloid leukemia (AML) cancer cell lines, we found that CARD8, and not NLRP1, mediates DPP8/9 inhibitor-induced pyroptosis in human T cells." (PMID 32796818, 2020).
atopic dermatitis (4 papers, 2021 to 2024). "Its function is not strictly linked to the innate immune system, as common inflammatory skin diseases (e.g. psoriasis and atopic dermatitis) are associated with the NLRP1 inflammasome and more importantly proinflammatory cytokines from IL-1 family." (PMID 36911693, 2023). "A single nucleotide polymorphism (SNP) in the NLRP1 gene from Swedish patients with atopic dermatitis was classified as a possible susceptibility for the occurrence of a disease manifestation, although not the only contributing factor." (PMID 36911693, 2023). "The missense variants, potentially affecting NLRP1 functions were predicted to be functionally significant in the susceptibility of atopic dermatitis." (PMID 33925158, 2021). "Polymorphisms in NLRP1 that could alter protein expression, can lead to a dysregulation in pathogen recognition and response in atopic dermatitis patients." (PMID 33925158, 2021). "The impaired wound healing and defense responses in atopic dermatitis might be caused by the downregulation of NLRP1 expression." (PMID 33925158, 2021).
autoinflammatory syndrome (4 papers, 2020 to 2026). A group of disorders of the innate immune system characterized by attacks of seemingly unprovoked inflammation without significant levels of either autoantibodies or autoreactive T cells more characteristic of autoimmune disease. "Rare germline mutations of NLRP1 cause its persistent activation, resulting in autoinflammatory syndromes." (PMID 42123364, 2026). "Interestingly, patients suffering from NLRP1-associated autoinflammatory syndrome (also characterized by high IL-18 and IL-1β levels) had higher peripheral blood transitional B cells, bearing the regulatory phenotype CD24highCD38highCD27low/neg." (PMID 38392193, 2024). "Furthermore, Grandemange reported a different missense mutation, p.Pro1214Arg in NLRP1, which caused NAIAD, an autoinflammatory syndrome with abnormal skin keratinization." (PMID 35784371, 2022). "Recent research has led to novel findings in inflammasome biology and genetics that altered the diagnosis and management of patients with autoinflammatory syndromes caused by NLRP3-, Pyrin-, NLRP1-, and NLRC4-inflammasomes and spurred the development of novel treatments." (PMID 32983099, 2020).
celiac disease (4 papers, 2013 to 2025). An autoimmune genetic disorder with an unknown pattern of inheritance that primarily affects the digestive tract. "In addition, the polymorphisms in NLRP3 and NLRP1 genes were associated with Celiac disease, suggesting their involvement in the predisposition to the disease." (PMID 39684769, 2024). "Single nucleotides polymorphisms (SNPs) in the NLRP1 gene may lead to an increased inflammasome activation, contributing, together with NLRP3, to a predisposition to Celiac disease." (PMID 39684769, 2024). "In fact, an abnormal activation of NLRP1 and/or NLRP3 inflammasomes results in an altered activation of IL-1β and NF-κB, contributing to the lack of immune tolerance common in Celiac disease." (PMID 39684769, 2024).
chronic myeloid leukemia (4 papers, 2020 to 2022). "The NLRP1 inflammasome was linked to multiple myeloma and chronic myeloid leukemia pathogenesis, whereas the NLRC4 was the key player in secondary HLH." (PMID 35897704, 2022). "The NLRP1 inflammasome was associated with myeloma and chronic myeloid leukemia, whereas NLRC4 was associated with hemophagocytic lymphohistiocytosis." (PMID 35897704, 2022). "In chronic myeloid leukemia (CML), overexpression of the NLRP1 inflammasome significantly increased the IL-1β levels and inhibited apoptosis." (PMID 35897704, 2022). "Recently, PERK and/or IRE1α branches of ER stress were found to enhance NLRP1 gene expression through the cAMP response element binding protein (CREB) in HeLa and chronic myelogenous leukemia cells." (PMID 33396632, 2020).
gastric cancer (4 papers, 2018 to 2025). A primary or metastatic malignant neoplasm involving the stomach. "Association between NLRP1/NLRP3 expression level and clinicopathological characteristics in patients with gastric cancer by Kaplan-Meier plotter." (PMID 36541912, 2022). "UALCAN analysis of TCGA data showed that NLRP1/NLRP3 expression level in primary gastric cancer was significantly higher than normal tissues (**p < 0.01, ***p < 0.001)." (PMID 36541912, 2022). "Lower levels of NLRP3, NLRP1, and AIM2 proteins were found in hepatocellular carcinoma (HCC), colorectal cancer (CRC), and gastric cancer (GC) compared to the adjacent normal tissue." (PMID 34298833, 2021).
lung carcinoma (4 papers, 2021 to 2026). "Lung epithelial cells usually express NLRP1 inflammasomes against pathogenic substances from the outside environment, but the definite function of NLRP1 in lung cancer remains unclear." (PMID 39258674, 2024). "This study utilized immunoinformatics and structural bioinformatics approaches to design and evaluate a multi-epitope vaccine targeting pyroptosis-associated antigens (CARD8, NAIP, NLRP1, and NLRP3), which are implicated in lung cancer immunology." (PMID 41857073, 2026). "Our data showed that NLRP1 overexpression reduced mitochondrial membrane potential and inhibited mitochondrial fission in lung cancer." (PMID 39258674, 2024). "Since the function of NLRP1 in lung cancer is still unclear, it is necessary to analyze the relationships between NLRP1 expression and some clinical parameters in LUAD patients." (PMID 33658393, 2021). "Given that lung cancer cells have a strong mitochondrial fission activity to promote tumor progression, it might be reasonable to infer that NLRP1 had the ability to inhibit tumor cell growth, possibly by promoting the transition of mitochondria from a fragmented state to a fused state." (PMID 39258674, 2024). "However, there are few studies on NLRC4 and NLRP1 in lung cancer, which need to be further studied." (PMID 36186792, 2022).
periodontitis (4 papers, 2020 to 2022). An acute or chronic inflammatory process that affects the tissues that surround and support the teeth. "In contrast, NLRP1 levels are decreased in the gingival tissues of mice with ligature-induced periodontitis." (PMID 34177950, 2021). "NLRP1 is one of the first discovered inflammasomes, but how it is activated remains unclear, especially in periodontitis." (PMID 36185327, 2022). "However, NLRP1 expression is significantly increased in human periodontal ligament cells (hPDLCs) challenged by advanced glycation end-products by activating the NF‐κB pathway, supporting its role in the influence of diabetes on periodontitis." (PMID 34177950, 2021). "In order to observe the different distribution of NLRP family intuitively, immunohistochemistry was applied to analyze the expression characteristics of NLRP1, NLRP2, NLRP3, NLRP6, and NLRP12 in full-thickness gingival tissue samples obtained from severe periodontitis patients and healthy people." (PMID 32903638, 2020).
prostate carcinoma (4 papers, 2021 to 2025). A carcinoma that arises from epithelial cells of the prostate gland. "Notably, the protein expression levels of NLRP1 showed a positive correlation with the Gleason score of prostate cancer." (PMID 40237399, 2025).
type 2 diabetes (4 papers, 2019 to 2026). "RKIP negatively regulates NLRP1 activation and NLRP3 and NLRC4-induced inflammatory body formation and plays an important role in the pathogenesis of type 2 diabetes." (PMID 36017103, 2022). "Glyburide, a common drug for type 2 diabetes (T2D) treatment, was the first identified NLRP3 inhibitor, though it does not inhibit NLRP1 or NLRC4-dependent IL-1β production." (PMID 41280719, 2025).